PFN2 (profilin 2)
Description:
Binds to actin and affects the structure of the cytoskeleton. At high concentrations, profilin prevents the polymerization of actin, whereas it enhances it at low concentrations. By binding to PIP2, it inhibits the formation of IP3 and DG.
Synonyms: D3S1319E; PFL
Tractability: Small molecule: it has a high-quality binding pocket. PROTAC: ubiquitination databases record sites on it; its protein half-life has been measured.
Gene: Protein-coding gene on chromosome 3 (149,964,904 to 150,050,788, reverse strand). Ensembl gene ENSG00000070087.
Subcellular location: Cytoplasm, cytoskeleton
Pathways (Reactome):
Developmental Biology: Signaling by ROBO receptors
Signal Transduction: RHO GTPases Activate Formins
Gene Ontology:
Molecular function: actin monomer binding; ATP hydrolysis activity; phosphatidylinositol-4,5-bisphosphate binding; protein binding; actin binding
Biological process: actin cytoskeleton organization; negative regulation of epithelial cell migration; negative regulation of ruffle assembly; positive regulation of actin filament bundle assembly; positive regulation of actin filament polymerization; positive regulation of stress fiber assembly; protein stabilization; regulation of actin filament polymerization; modification of postsynaptic actin cytoskeleton; modulation of chemical synaptic transmission; presynaptic actin cytoskeleton organization; presynaptic modulation of chemical synaptic transmission
Cellular component: extracellular exosome; cytoplasm; cytoskeleton; glutamatergic synapse; postsynapse; presynapse; Schaffer collateral - CA1 synapse
Genetic constraint (gnomAD): Loss-of-function variants: 8 observed, 10.28 expected, observed/expected ratio (o/e) 0.78, 90% interval 0.46 to 1.4. The upper end of that interval is the gene's LOEUF score, 1.4, which puts it in group 5 of 6, group 1 being the genes least tolerant of losing a copy. Missense variants: 105 observed, 155.67 expected, observed/expected ratio (o/e) 0.67, 90% interval 0.57 to 0.79. Synonymous variants: 75 observed, 61.43 expected, observed/expected ratio (o/e) 1.22, 90% interval 1.01 to 1.48.
Homologues: Orthologues: guinea pig PFN2 (100% identical), dog PFN2 (99% identical), mouse Pfn2 (99% identical), rat Pfn2 (96% identical), chimpanzee PFN2 (93% identical), zebrafish pfn2a (81% identical), tropical clawed frog pfn2 (80% identical), macaque PFN2 (79% identical), zebrafish pfn2b (69% identical), rabbit PFN2 (65% identical). Paralogues in human: PFN1 (59% identical), PFN3 (41% identical).
Diseases named in the same sentence as PFN2 in open-access papers:
PFN2 is named in the same sentence as 52 diseases in open-access papers, as found by Europe PMC text mining. Sharing a sentence is not in itself a finding about the gene and the disease. The quoted sentences say what the papers report.
breast carcinoma (11 papers, 2021 to 2025). "The increased expression of PFN2 expression has been linked to worse prognosis in breast cancer and found to accelerate small-cell lung cancer by promoting tumor-related blood vessel formation." (PMID 40299352, 2025). "High PFN2 expression has also been linked to poor prognosis in breast cancer, where it facilitates metastasis through Smad2 upregulation." (PMID 41395115, 2025). "Recent reports have shown that aberrant expression of PFN2 is associated with poor prognosis in breast cancer and that PFN2 is regulated by FOXD2-AS1 and OCT439." (PMID 35413990, 2022). "Zhao and colleagues further demonstrated that miR-223 can be sponged by circABCB10, contributing to increased expression of PFN2 and to breast cancer progression, both in vitro and in vivo." (PMID 39125761, 2024). "In breast cancer, hnRNPA2B1 can directly bind to the UAGGG locus of PFN2 mRNA to reduce its stability, and thereby, inhibit the metastasis of breast cancer." (PMID 34094986, 2021). "For example, although both PFN1 and PFN2 are expressed in breast cancer cells, they have distinct effects on cell migration and invasion ability." (PMID 33590416, 2021). "MiR-223 may suppress the development of breast cancer by targeting multiple oncogenic transcripts, including epithelial cell transforming 2 (ECT2), Profilin 2 (PFN2) and NLRP3." (PMID 39125761, 2024). "Circ-ADAM9 is upregulated in breast cancer, and inhibition of circ-ADAM9 could induce breast cancer radiosensitivity and apoptosis by acting as a decoy of miR-383-5p to regulate the level of PFN2." (PMID 38186573, 2023). "In breast cancer, miR-150-5p suppressed PFN2 in a sequence-dependent manner, and the long non-coding RNA FOXD2 adjacent the opposite strand of RNA1 (FOXD2-AS1)/miR-150-5p/PFN2 axis regulated malignancy and tumorigenesis." (PMID 35327465, 2022).
lung carcinoma (9 papers, 2016 to 2024). "In lung cancer, the actin-binding protein profilin-2 binds to and thereby prevents HDAC1′s access to the promoters of SMAD2 and SMAD3, which causes activation and promotes EMT and angiogenesis in lung cancer cells." (PMID 38279330, 2024). "A previous study has shown that PFN2 promotes the growth and metastasis of lung cancer by epigenetic regulation of Smad2 and Smad3." (PMID 33234737, 2020). "In OSCC, PFN2 serves as a negative regulator of tumor growth and aggressiveness, whereas PFN2 significantly increases migration and invasion ability of lung cancer and colorectal cancer stem cells." (PMID 27188458, 2016). "For instance, one research showed that PFN2 mRNA levels and protein were significantly up-regulated in lung cancer tissues, whilst PFN2 overexpression strongly promoted lung cancer migration and invasion." (PMID 27188458, 2016). "Notably, a previous study showed that miR-30a-5p suppressed the expression of PFN2 in lung cancer cell lines." (PMID 35886008, 2022). "In lung cancer cells, miR-30a-5p negatively regulates PFN2 and inhibited EMT and invasion." (PMID 35327465, 2022). "In lung cancer, PFN2 has been identified as a critical activator of TGF-β/Smad signal-inducing EMT." (PMID 27188458, 2016). "Expression of PFN2 induced the transactivation of Smad2 and Smad3, and these transmission factors enhanced TGF-β-induced EMT and angiogenesis in lung cancer." (PMID 35327465, 2022). "Previous studies have shown that PFN2 contributes to epithelial-mesenchymal transition (EMT) and regulates Smad2/3 expression in non–small-cell lung cancer." (PMID 33234737, 2020). "Moreover, Pfn2 correlates with SMAD3 expression in human lung cancers, where its overexpression promotes lung cancer growth and metastasis." (PMID 33672325, 2021). "However, data from the TCGA database and the human protein atlas showed that PFN2 is highly expressed in non–small cell lung cancer (NSCLC) but not in normal lung tissues." (PMID 33234737, 2020).
colorectal cancer (8 papers, 2016 to 2025). A primary or metastatic malignant neoplasm that affects the colon or rectum. "Loss of or decreased activity of Pfn2 has been correlated with colorectal cancer cell metastatic and migratory capacities, and knockdown of a Pfn1-interacting protein regulates the advancement of colorectal tumors." (PMID 38730628, 2024). "Inhibition of Pfn2 has been shown to contribute to colorectal cancer metastatic and migratory capacities." (PMID 38730628, 2024). "Profilin-2, as a downstream regulator of TGF-β/Smad signaling, plays a pro-tumoral role linked to EMT processes in colorectal cancer." (PMID 39086667, 2023). "Another study reported that up-regulated PFN2 expression in colorectal cancer stem cells enhanced the ability of migration and invasion." (PMID 27188458, 2016). "Nevertheless, PFN2 significantly enhanced migration and invasion ability of HT29 human colorectal cancer stem cells." (PMID 27188458, 2016).
small cell lung carcinoma (7 papers, 2020 to 2025). Small cell lung cancer (SCLC) is a highly aggressive malignant neoplasm, accounting for 10-15% of lung cancer cases, characterized byrapid growth, and early metastasis. "Another study showed that overexpression of PFN2 enhanced the aggressiveness of small cell lung cancer (SCLC), including cell proliferation, migration, and invasion." (PMID 35886008, 2022). "A recent study reported that PFN2 is involved in small cell lung cancer metastasis and angiogenesis through exosomes." (PMID 35327465, 2022). "Most recently, we found that PFN2 and exosomal PFN2 could promote small cell lung cancer growth and metastasis as well as tumor angiogenesis, we speculated that exosomal PFN2 might also promote angiogenesis on cardiac tissue after MI." (PMID 35479278, 2022). "Very recently, we found that exosomal PFN2 from small cell lung cancer (SCLC) cells could promote the growth of these cells, as well as significantly improve the proliferation, migration, and tube formation of ECs." (PMID 35479278, 2022). "In small-cell lung cancer (SCLC), PFN2 is significantly upregulated in tumor tissues relative to normal lung, where it supports tumor angiogenesis and metastatic dissemination." (PMID 40981267, 2025). "Other studies have also found that PFN2 has different expression patterns and effects in NSCLC, small cell lung cancer, and gastric cancer." (PMID 34917619, 2021).
esophageal squamous cell carcinoma (5 papers, 2016 to 2025). Esophageal squamous cell carcinoma (ESCC) is a type of esophageal carcinoma (EC) that can affect any part of the esophagus, but is usually located in the upper or middle third. "Additionally, PFN2 drives the progression and metastasis of esophageal squamous cell carcinoma (ESCC)." (PMID 40299352, 2025). "In esophageal squamous cell carcinoma, a high PFN2 level is related to short overall survival." (PMID 34917619, 2021). "In esophageal squamous cell carcinoma (ESCC), PFN2 protein expression was markedly increased gradually from low-grade intraepithelial neoplasia to ESCC, and high expression was positively correlated with the depth of invasion and lymph node metastasis." (PMID 35327465, 2022).
Anxiety (4 papers, 2020 to 2023). Intense feelings of nervousness, tension, or panic often arise in response to interpersonal stresses. "Among them, 63 protein-coding genes, including Atat1 and Pfn2 known to be associated with anxiety-related or exploration behavior in mice, respectively, were located surrounding the identified candidate polymorphisms." (PMID 37147374, 2023). "When considering NPDs of interest, depression, and anxiety alone, the strongest pleiotropic effects of single genes, i.e. highest number of associations with disorders, were observed for PFN2, HTRA1, SCRN1, ATAT1, and SYN3." (PMID 37461513, 2023). "We illustrate the utility of the dataset by demonstrating that knockdown in the interpeduncular nucleus of a differentially expressed mRNA, that encoding profilin 2, is sufficient to induce anxiety-related behavior." (PMID 31965003, 2020). "The synaptic roles of Pfn2 and its link to behaviors such as anxiety led us to hypothesize that down-regulation of Pfn2 during acute nicotine withdrawal contributes to the neural activation in the IPN during withdrawal, increasing anxiety-associated behaviors." (PMID 31965003, 2020). "Supporting this hypothesis, we show that knockdown of Pfn2 expression in the IPN of nicotine-naïve mice was sufficient to increase anxiety as measured by EPM, mimicking behaviors observed in WT mice during acute nicotine withdrawal." (PMID 31965003, 2020). "Importantly, profilin 2 knockdown in the ventral tegmental area did not affect anxiety behavior." (PMID 31965003, 2020). "The effect of Pfn2 knockdown is also specific to the IPN, as knockdown within the neighboring VTA does not increase anxiety." (PMID 31965003, 2020). "Interestingly, knockdown of Pfn2 in the IPN, but not in the VTA, results in an increased anxiety-related phenotype, supporting a role in withdrawal-induced anxiety." (PMID 33828466, 2021).
osteosarcoma (3 papers, 2021 to 2022). A usually aggressive malignant bone-forming mesenchymal neoplasm, predominantly affecting adolescents and young adults. "Likewise, TUG1 could impede osteosarcoma cells proliferation, migration, and invasion by miR-140-5p/PFN2 axis." (PMID 33639865, 2021).
triple-negative breast carcinoma (3 papers, 2021 to 2024). An invasive breast carcinoma which is negative for expression of estrogen receptor (ER), progesterone receptor (PR), and human epidermal growth factor receptor 2 (HER2). "Previous studies have confirmed that miR-1287-5p interacts with the 3′-UTR of PFN2 and enhances migration, invasion, proliferation, and epithelial-to-mesenchymal transition of triple-negative breast cancer cells." (PMID 38539084, 2024). "PFN2 has been reported to be highly expressed in triple-negative breast cancer (TNBC); it could promote the proliferation, migration, and invasion of TNBC cells and may be partially responsible for the worsened survival associated with high PFN2 levels." (PMID 34917619, 2021). "In triple-negative breast cancer (TNBC), high expression of PFN2 was related to a poorer prognosis (10-year overall survival and relapse-free survival)." (PMID 35327465, 2022).
esophageal cancer (2 papers, 2016 to 2018). A primary or metastatic malignant neoplasm involving the esophagus. "For the Han population, the IHC analysis displayed that the frequency of PFN2 protein overexpression was lowest in the NEE tissue (8.1 %), but its frequency increased gradually along with the progress of esophageal cancer, with 40.4 % (21/52) of LGIN and 91.0 % (30/33) of HGIN." (PMID 27188458, 2016).
gastric cancer (2 papers, 2007 to 2021). A primary or metastatic malignant neoplasm involving the stomach. "In another example, overexpression of PFN2 (Regulation of actin cytoskeleton) and UBS (stress response) has been associated with lymph node metastasis of gastric cancer and colon cancer respectively." (PMID 17900369, 2007).
head and neck cancer (2 papers, 2020 to 2022). A primary or metastatic malignant neoplasm affecting the head and neck. "Furthermore, PFN2 was shown to be upregulated in head and neck cancers and its knockdown inhibited proliferation, invasion and migration of these cells." (PMID 35413990, 2022). "The function of PFN2 has been reported in head and neck cancers, ovarian cancer, and NSCLC." (PMID 33234737, 2020).
head and neck squamous cell carcinoma (2 papers, 2020 to 2022). A squamous cell carcinoma that arises from any of the following anatomic sites: lip and oral cavity, nasal cavity, paranasal sinuses, pharynx, larynx, and salivary glands. "In head and neck squamous cell carcinoma (HNSCC), downregulation of PFN2 reduced phosphorylation/expression of AKT, GSK-3β, and β-catenin, leading to reduced invasion and metastasis." (PMID 33171868, 2020).
inflammatory bowel disease (2 papers, 2015 to 2025). A spectrum of small and large bowel inflammatory diseases of unknown etiology. "Consistent with that, another group showed upregulation of the Abi2 gene together with the genes for the fibroblast growth factor, profilin-2, and radixin during tumorigenesis of inflammatory bowel disease- (IBD-) associated CRC." (PMID 26345720, 2015).
intraepithelial neoplasia (2 papers, 2016 to 2022). A precancerous neoplastic process that affects the squamous, glandular, or transitional cell epithelium without evidence of invasion. "Compared with normal esophageal epithelium (NEE), PFN2 protein expression was markedly increased in low-grade intraepithelial neoplasia (LGIN), high-grade intraepithelial neoplasia (HGIN), and ESCC, increased gradually from LGIN to ESCC, and finally reached high grade in HGIN in the Han population." (PMID 27188458, 2016).
myocardial infarction (2 papers, 2022 to 2025). Gross necrosis of the myocardium, as a result of interruption of the blood supply to the area, as in coronary thrombosis. "Elevated PFN2 levels in serum and exosomes from myocardial infarction patients suggest a role in post-injury angiogenesis." (PMID 40981267, 2025). "Profilin overexpression has also been associated with vascular hypertrophy and hypertension, and elevated PFN2 levels were recently reported in the serum and exosomes of myocardial infarction patients, implicating Profilin in acute cardiovascular events." (PMID 40981267, 2025). "Moreover, exosomal PFN2 derived from ECs has a significant therapeutic effect in mice with myocardial infarction." (PMID 35479278, 2022).
ovarian carcinoma (2 papers, 2020 to 2024). A malignant neoplasm originating from the surface ovarian epithelium. "PFN2 has also been investigated in colorectal cancer cells and in ovarian cancer." (PMID 33234737, 2020).
prostate carcinoma (2 papers, 2022 to 2024). A carcinoma that arises from epithelial cells of the prostate gland. "In prostate cancer, OCT1 binds and upregulates PFN2 to stimulate tumor growth." (PMID 38605354, 2024).
artery occlusion (1 paper, 2022). "We monitored the dynamic changes in PFN2, exosomes, and exosomal PFN2 after coronary artery occlusion, all of which increased in the serum of rats with MI and reached maximal exosomes numbers earlier than the exosomal PFN2, and PFN2." (PMID 35479278, 2022).
autism spectrum disorder (1 paper, 2025). A spectrum of developmental disorders that includes autism, and Asperger syndrome. "PFN2 was also found in protein complexes with proteins that have been implicated in or are causative of autism spectrum disorder." (PMID 40078324, 2025). "We find that these behaviors are robustly altered in the Pfn2−/− mouse model, which could therefore represent an interesting in vivo model to study or validate one possible pathway causing autism spectrum disorder." (PMID 40078324, 2025).
autistic disorders (1 paper, 2025). "In conclusion, the Pfn2 knock-out mouse could provide a model to study therapeutic interventions for a subset of autistic disorders dependent on increased excitation/inhibition ratio in the nervous system." (PMID 40078324, 2025).
cholesteatoma (1 paper, 2014). A pathologic process characterized by the proliferation of keratinizing squamous epithelium resulting in the accumulation of keratin and cells in the middle ear and/or mastoid. "Profilin-2 (PFN2) was deficient in the three cholesteatoma replicates, but was found in high levels in all three replicates of the tympanic membrane, EACS, and mucosa." (PMID 25093596, 2014).
Hyperglycemia (1 paper, 2021). An increased concentration of glucose in the blood. "The present study indicated that ets1 cooperated with KMT5A to transcribe PFN2, thus contributing to hyperglycemia-induced EndMT in the glomerular endothelial cells of DN patients and rats." (PMID 34238215, 2021). "However, whether PFN2 participates in hyperglycemia-mediated EndMT in endothelial cells has not been reported." (PMID 34238215, 2021).
infarction (1 paper, 2022). A localised pathological necrosis of tissue resulting from obstruction of the blood supply usually by a thrombus, an embolus, or vascular torsion. "In summary, PFN2 and endothelial exosomal PFN2 promoted EC angiogenic ability and protected ECs from inflammation, consequently alleviating infarction and enhancing cardiac function in MI, mediated by the PI3K-PFN2-ERK axis." (PMID 35479278, 2022).
lipoma (1 paper, 2017). A benign, usually painless, well-circumscribed lipomatous tumor composed of adipose tissue. "PFN2 (profilin 2), BTG1 (BTG anti-proliferation factor 1), LPP (LIM domain containing preferred translocation partner in lipoma) and CDK6 (cyclin dependent kinase 6) came to prominence as significant genes that have important effects in the cancer progression." (PMID 28981542, 2017).
lymph node metastasis (1 paper, 2016). "PFN2 expression was positively correlated with invasion depth and lymph node metastasis." (PMID 27188458, 2016).
metastasis (1 paper, 2016). The spread or migration of cancer cells from one part of the body (where they first appeared) to another. "In Han patients, a high PFN2 expression more frequently occurred in ESCC tissue with deep invasion (P = 0.004), and a positive lymph node metastasis occurred in Kazakh patients (P = 0.010)." (PMID 27188458, 2016).